AIF1 (allograft inflammatory factor 1)
Diseases named in the same sentence as AIF1 in open-access papers (continued):
Sharing a sentence is not in itself a finding about the gene and the disease.
autoimmune disease (6 papers, 2012 to 2025). A disorder resulting from loss of function or tissue destruction of an organ or multiple organs, arising from humoral or cellular immune responses of the individual to their own tissue constituents. "Several single-nucleotide polymorphisms (SNPs) have been identified in the AIF-1 gene as associated with autoimmune diseases." (PMID 30252881, 2018). "Because its pro-inflammatory role, AIF-1 is involved in various inflammatory pathological processes such as allograft rejection, autoimmune diseases, inflammatory central nervous system injury." (PMID 30252881, 2018). "Moreover, AIF-1 is involved in some model of autoimmune diseases such as experimental autoimmune uveitis, encephalomyelitis and neuritis." (PMID 30252881, 2018). "Another gene that is independently associated with autoimmune diseases outside of non-antigen-binding HLA alleles is allograft inflammatory factor-1 (AIF1)." (PMID 22928105, 2012). "An increasing number of studies suggest that Aif1 may play a critical role in the immune response to allo- or auto-antigens and inflammatory responses, and its expression level parallels the autoimmune disease stage." (PMID 29245939, 2017).
hepatocellular carcinoma (6 papers, 2019 to 2024). A malignant tumor that arises from hepatocytes. "Silencing of AIF1 expression resulted in a reduction in cell proliferation and migration in human hepatocellular carcinoma cells." (PMID 38521928, 2024). "The role of AIF-1 in cancer has been demonstrated in past works, mainly focused on hepatocellular carcinoma, breast, lung and other types of cancer." (PMID 38785507, 2024). "In relation to HCC, AIF1 enhances proliferation of the human hepatoma cell line HepG2 through activation of the insulin growth factor/insulin-like growth factor-1 receptor (IGF/IGF1R) axis and its downstream signaling pathway." (PMID 37237507, 2023). "It is reported that in hepatocellular carcinoma macrophages overexpressing AIF1 promoted tumor migration and proliferation of tumor cells." (PMID 33186124, 2020). "For example, CSF1 enhances the progression of hepatocellular carcinoma by inducing AIF1 expression in TAMs." (PMID 31629410, 2019). "Zhang revealed that AIF1 was upregulated in hepatocellular carcinoma." (PMID 38521928, 2024). "In addition, AIF1 may play a significant role in the pathophysiology and progression of gastric cancer, hepatocellular carcinoma as well as colorectal cancer." (PMID 38521928, 2024).
Insulin resistance (6 papers, 2013 to 2026). Increased resistance towards insulin, that is, diminished effectiveness of insulin in reducing blood glucose levels. "Additionally, AIF1 mRNA levels were positively correlated with insulin resistance as evaluated by the homeostasis model assessment for insulin resistance (HOMA)." (PMID 37237507, 2023). "We also observed that AIF-1 expression was associated to a negative metabolic profile (i.e. parameters of insulin resistance)." (PMID 24267103, 2013). "In multiple regression with BMI and AIF-1 mRNA levels as independent factors, we found that WAT AIF-1 expression was independently correlated with insulin resistance as determined by HOMAIR (partial r = 0.369, P = 0.0042) in this cohort of women." (PMID 24267103, 2013). "Expression of AIF-1 was inversely correlated with insulin sensitivity as assessed by insulin tolerance test (KITT), and circulating levels of adiponectin (P = 0.02), and positively correlated with insulin resistance as estimated by HOMA (=0.0042)." (PMID 24267103, 2013).
Autoimmunity (5 papers, 2017 to 2025). The occurrence of an immune reaction against the organism's own cells or tissues. "A total five genes (Fes, Aif1, Gata3, Tlr6, Tlr2) were identified as hub genes that are most likely related to the silicone-induced immune response, four of which (Aif1, Gata3, Tlr6, Tlr2) have been associated with autoimmunity as target genes or disease markers." (PMID 29245939, 2017). "Strikingly, most of these hub genes (Tlr2, Tlr6, Aif1, Gata3) have also been reported to be crucial in autoimmunity development." (PMID 29245939, 2017). "A total five genes (Fes, Aif1, Gata3, Tlr6, Tlr2) and nine pathways were identified as central participants in the silicone-induced immune response, most of which are also related to autoimmunity." (PMID 29245939, 2017). "Remarkably, aside from effects on autoimmunity there are no data reporting about a significant physiological role of AIF1 for glomerular function." (PMID 30001384, 2018).
diabetic kidney disease (5 papers, 2013 to 2025). Progressive kidney disorder caused by vascular damage to the glomerular capillaries, in patients with diabetes mellitus. "Several studies have linked AIF1 to chronic kidney disease (CKD) and diabetic kidney disease (DKD)." (PMID 37237507, 2023). "Aif1 promotes inflammation and OS in diabetic nephropathy through the miR-34a/ATG4B pathway." (PMID 36826575, 2023). "In a different study, these authors also suggested that AIF-1 could be a marker for diabetic nephropathy as well as activated macrophages." (PMID 24267103, 2013). "Furthermore, in this study, we demonstrated for the first time that AIF-1 regulated the level of inflammation, oxidative stress, and autophagy in glomerular endothelial cells through miR-34a/ATG4B pathway in diabetic kidney disease." (PMID 36345369, 2022).
lung carcinoma (5 papers, 2019 to 2025). "SPINK2 and at least one of the correlated genes, AIF1 (allograft inflammatory factor 1), showed higher expression in female NKs than in male NKs from either PBMCs or the microenvironment of lung cancer." (PMID 36936975, 2023). "The possible functional role of AIF-1 in NSCLC was further explored in a human lung cancer cell line." (PMID 36520870, 2022). "Our findings suggest that AIF-1 might play an important role in the development and progression of lung cancer." (PMID 36520870, 2022). "This is supported by our findings showing that AIF-1 expression was significantly, positively correlated with CD68 expression in lung cancer and co-localized with CD68+ macrophages." (PMID 36520870, 2022).
autism (4 papers, 2014 to 2020). Persistent deficits in social interaction and communication and interaction as well as a markedly restricted repertoire of activity and interest as well as repetitive patterns of behavior. "In contrast, the expression of microglial markers TREM2, DAP12, CX3CR1, and AIF1 were lower in autism tissue than in control tissue, with fold changes of 0.780 (P = 0.0056), 0.797 (P = 0.0083), 0.659 (P = 0.0029), and 0.808 (P = 0.0052), respectively." (PMID 24410870, 2014).
chronic kidney disease (4 papers, 2022 to 2025). Impairment of the renal function secondary to chronic kidney damage persisting for three or more months. "We further demonstrated increased expression of AIF-1 in human kidney biopsies from native kidneys with acute kidney injury or chronic kidney disease, as well as in biopsies from kidney allografts undergoing acute or chronic rejection." (PMID 39836477, 2025). "Mechanistically, aldosterone may induce vascular calcification related to chronic renal failure via the AIF1 pathway." (PMID 38898508, 2024). "In conclusion, our study indicated that Aldo may induce vascular calcification related to chronic renal failure via the AIF-1 pathway which may provide a potential therapeutic target." (PMID 35937793, 2022).
retinal ischemia (4 papers, 2017 to 2024). A ischemic disease that involves the retina. "The microglia marker Aif1 is upregulated in this cell population with a peak around 3 days after retinal ischemia/reperfusion injury, and mRNA levels decline by day 7 after injury." (PMID 38388518, 2024).
scrapie (4 papers, 2016 to 2025). A fatal disease of the nervous system in sheep and goats, characterized by pruritus, debility, and locomotor incoordination. "Furthermore, although activated microglia were seen in BE infected mice by IHC, based on the expression levels of microglial markers, Gpr84 and Aif1, the number of activated microglia was less in BE than in scrapie." (PMID 27046083, 2016).
delirium (3 papers, 2022 to 2025). A disorder characterized by confusion; inattentiveness; disorientation; illusions; hallucinations; agitation; and in some instances autonomic nervous system overactivity. "LM‐ and AS‐induced delirium led to microglial activation in the hippocampus as evidenced by up‐regulation of microglial activation‐related genes (such as Il6ra, Tyrobp, Cd68, Aif1, Csf1r, and Trem2) and of relevant inflammatory factors (such as Il‐1β, Tnfα, Ccl2, Ccl5, and Ccl8)." (PMID 35713240, 2022).
gastric cancer (3 papers, 2023 to 2024). A primary or metastatic malignant neoplasm involving the stomach. "AIF1 silencing in gastric cancer BGC-823 and SGC7901 cell lines led to enhanced proliferation and upregulation of β-catenin, a molecule that has been demonstrated to play an important role in gastric cancer." (PMID 37237507, 2023). "Yang provided evidence that the level of AIF-1 expression may serve as a protective prognostic indicator for gastric cancer by regulating β-catenin." (PMID 38521928, 2024).
liver cancer (3 papers, 2024 to 2025). An epithelial or non-epithelial malignant neoplasm that arises from the liver. "In a liver cancer model induced by DEN exposure, AIF1+CSF1R+ MSCs exhibiting elevated expression of sirtuin 1 (SIRT1) was identified within liver tissues undergoing chronic inflammation prior to the onset of cancer." (PMID 40676710, 2025). "In rat primary liver cancer models induced by diethylnitrosamine (DEN), a distinct population of AIF1+CSF1R+ MSCs was identified during the chronic inflammation stage." (PMID 40676710, 2025). "AIF1 induction by TNF-α stimulation promotes macrophage recruitment and liver inflammation, affecting the liver microenvironment and potentially contributing to liver cancer development." (PMID 39254691, 2024).
malignant glioma (3 papers, 2011 to 2021). A grade III or grade IV glioma arising from the central nervous system. "AIF-1 expression, which has been established as a pro-inflammatory gene product of active NF-κB, has been found in various human cells and tissues such as macrophages, thymus, liver, lung, and subtypes of invasive malignant gliomas." (PMID 21479220, 2011).
medulloblastoma (3 papers, 2019 to 2025). A malignant, invasive embryonal neoplasm arising from the cerebellum. "We found that there was a significant increase in AIF1 transcription in SHH medulloblastoma, moreso than in any other medulloblastoma subgroup (P < 0.0001, one-way ANOVA)." (PMID 31160587, 2019).
metastatic tumors (3 papers, 2022 to 2024). "The expression of various antioxidants, including PRX1, GPX1, UBE2N, and AIF1, was significantly higher in metastatic tumors." (PMID 39795567, 2024).
temporal lobe epilepsy (3 papers, 2017 to 2025). A localization-related (focal) form of epilepsy characterized by recurrent seizures that arise from foci within the temporal lobe, most commonly from its mesial aspect. "Astro- and microgliosis, along with elevated expression of Gfap and Aif1 genes, are well-documented feature of both clinical temporal lobe epilepsy and the lithium-pilocarpine model." (PMID 41009625, 2025).
type 1 diabetes (3 papers, 2020 to 2023). "Regarding type 1 diabetes, biobreeding (BB) rats showed AIF1-expressing macrophage accumulation during insulitis, affecting pancreatic islets." (PMID 37237507, 2023). "Additionally, AIF1 injection led to increased glycemia, impaired insulin expression and accelerated type 1 diabetes." (PMID 37237507, 2023).
ankylosing spondylitis (2 papers, 2024). An autoimmune chronic inflammatory disorder characterized by inflammation in the vertebral joints of the spine and sacroiliac joints. "Among them, AIF1 and IL23R are associated with decreased risk of ankylosing spondylitis; MICA, MAPK14, and ATF6B are linked to increased risk of ankylosing spondylitis." (PMID 38835753, 2024). "AIF1, ankylosing spondylitis characterized by a systemic inflammatory response, also provides us with a research direction on how it regulates the inflammatory response of the synovium and ligament and the involvement of related inflammatory mediators." (PMID 39254691, 2024).
breast tumor (2 papers, 2014 to 2018). "The present study aims to explore potential functions of two AIF1 isoforms (AIFv1 and AIF1v3) in breast tumors of varying severity and breast adipose tissue by evaluating their expression and relationship to metabolic and clinical parameters of BC patients." (PMID 30386176, 2018). "We also provide pertinent information on how both AIF1 isoforms relate to the breast tumor microenvironment." (PMID 30386176, 2018). "Given that AIF1 in highly expressed in the less severe breast tumors, it may prove useful as a favorable prognostic factor for BC." (PMID 30386176, 2018).
colon tumors (2 papers, 2017 to 2024). "One possible mechanism of Aif1-independent uptake is IgA-mediated transcytosis by Dectin-1 because it has recently been reported that Dectin-1 acts on IgA-mediated transcytosis in M-like cells derived from Caco-2 cells, a human colonic cancer cell line, and mouse M cells." (PMID 28224999, 2017).
colorectal cancer (2 papers, 2024). A primary or metastatic malignant neoplasm that affects the colon or rectum. "AIF-1 overexpression promoted the apoptosis of colorectal cancer cells by activating the p38 MAPK pathway." (PMID 38521928, 2024). "Both are associated with better prognosis in patients with colorectal cancer and clustered with known TAM-associated genes such as P2RY12 and AIF1." (PMID 38386085, 2024). "In addition, Ai-founded AIF1 plays the role of a tumor suppressor in colorectal cancer cells by inhibiting cell proliferation, suppressing cell migration, and inducing cell apoptosis." (PMID 38521928, 2024).
Crohn disease (2 papers, 2022). A gastrointestinal disorder characterized by chronic inflammation involving all layers of the intestinal wall, noncaseating granulomas affecting the intestinal wall and regional lymph nodes, and transmural fibrosis. "To analyze the possible usefulness of AIF-1 as a biomarker in Crohn’s disease, we studied the levels of AIF-1 in a cohort of naïve patients treated with anti-TNF (infliximab or adalimumab)." (PMID 35327530, 2022). "Therefore, we studied the levels of AIF-1 in Crohn’s disease (CD)." (PMID 35327530, 2022). "The mechanistic role played by serum AIF-1 in Crohn’s disease currently remains unknown." (PMID 35327530, 2022). "More recently, AIF-1 increase has been described in serum and tissue of rats and human colon mucosa during DSS-induced experimental colitis or Crohn’s disease, respectively." (PMID 36671729, 2022).
esophageal cancer (2 papers, 2023 to 2025). A primary or metastatic malignant neoplasm involving the esophagus. "In esophageal cancer, AIF-1 has emerged as a novel prognostic gene related to the tumor microenvironment, immune infiltration, and TIGIT expression." (PMID 37014322, 2023).
Hyperbilirubinemia (2 papers, 2016). An increased amount of bilirubin in the blood. "Detection in the brain section of the cell double positive for luciferase and the microglial marker AIF1 suggests that hyperbilirubinemia is associated, at least in part, with increased proliferation of microglial cells." (PMID 28036021, 2016).
lung adenocarcinoma (2 papers, 2022). A carcinoma that arises from the lung and is characterized by the presence of malignant glandular epithelial cells. "Additionally, the effects of AIF-1 expression on the proliferation and migration of human lung adenocarcinoma cells and their secretion of IL-6 and VEGF were assessed, and the underlying mechanisms were investigated." (PMID 36520870, 2022). "Gene correlation analyses of TCGA data revealed that several genes associated with p38-MAPK and JAK/STAT3 signaling were strongly positively correlated with AIF-1 expression in lung SCC and lung adenocarcinoma." (PMID 36520870, 2022). "Pearson correlation analyses of TGCA data showed that AIF-1 expression was significantly positively correlated with CD68 expression (a macrophage marker) in NSCLC (r = 0.600, P < 0.001), lung SCC (r = 0.590, P < 0.001) and lung adenocarcinoma (r = 0.600, P < 0.001)." (PMID 36520870, 2022).
non-small cell lung carcinoma (2 papers, 2022 to 2023). A group of at least three distinct histological types of lung cancer, including non-small cell squamous cell carcinoma, adenocarcinoma, and large cell carcinoma. "In non-small cell lung cancer (NSCLC), AIF1 expression was upregulated, and associated with metastasis, higher TNM stage, and poorer survival." (PMID 37237507, 2023). "This study aimed to investigate the role of AIF-1 in the development and progression of non-small cell lung cancer (NSCLC)." (PMID 36520870, 2022).